CTLA4 (cytotoxic T-lymphocyte associated protein 4)
Diseases named in the same sentence as CTLA4 in open-access papers (continued):
Sharing a sentence is not in itself a finding about the gene and the disease.
tumor (continued). "Pre-clinical and clinical data employing local ablative RT with OX40 agonistic antibody, systemic IL-2, or anti-CTLA-4 determine that signaling through CD25 and OX40 increase T-cell responses against tumor-associated antigens." (PMID 24672524, 2014). "T cell co-inhibitory molecules, such as CTLA-4 and PD-1, have been validated through numerous pre-clinical and clinical trials, as critical mediators of tumor immune suppression." (PMID 24829758, 2014). "The increased production of IFNγ in the tumor and spleen of WT mice treated with RT + anti-CTLA-4 in the presence of CD1d blockade supports this interpretation." (PMID 25349699, 2014). "The results indicated that 64Cu-DOTA-anti-CTLA-4 mAb is useful for the noninvasive imaging of CTLA-4 expression in tumor." (PMID 25365349, 2014). "It is known that CTLA-4 blockade removes suppressive signals and allows expansion of tumor-specific T cells, in particular of CD4+ effectors." (PMID 25013914, 2014). "Both CTLA-4 and PD-1 have been targeted by inhibitory antibodies as an adjuvant therapy in cancer in attempt to enhance T-cell activation and tumor immunity." (PMID 25374843, 2014). "While single agent CTLA-4 or PD-1 pathway blockade has demonstrated clear anti-tumor activity across multiple tumor types, responding patients are still in the minority, underscoring the importance of improving upon present options." (PMID 25642417, 2014). "Further, the combination of anti-CTLA-4 and PD-1 antibodies achieved an even more effective anti-tumor response." (PMID 25538704, 2014). "Tremelimumab, also an antibody against CTLA-4, has been evaluated in multiple tumor types (Calabrò, Danielli, Sigalotti, & Maio, 2010; Tarhini, 2013)." (PMID 26328216, 2014). "RT-PCR showed that CTLA-4 expression was dramatically decreased in the CT26 tumor tissues from the tumor-bearing BALB/c nude mice, compared with those from the tumor-bearing BALB/c mice." (PMID 25365349, 2014). "Blockade of CTLA-4 by antibodies prevents the inhibitory signal to the T cell resulting in an enhanced T cell response against tumor cells and improved anti-tumor activity." (PMID 24904823, 2014). "This prompted us to extend the analysis of H-1PV anti-tumor effects to the SW480 system in combination with the anti-CTLA-4 antibody tremelimumab." (PMID 24822170, 2014). "Binding of CTLA-4 expressed on TREG cells to CD80 and CD86 on dendritic cells is believed to suppress T cell responses through the up-regulation of IDO expression, thus revealing another mechanism through which CTLA-4 can contribute to tumor antigen tolerance." (PMID 24904823, 2014). "As a means to instigate immune suppression, tumor cells often engage immune checkpoint molecules, such as CTLA-4 and PD1, which downregulate pathways of T cell activation." (PMID 24811491, 2014). "CD1d blockade did not have any effect by itself on tumor growth or survival, but it improved control of the irradiated tumor (p < 0.05) and survival (p < 0.05) of mice treated with RT and anti-CTLA-4." (PMID 25349699, 2014). "This was the first study reporting immunological changes in both tumor tissues and peripheral blood after treatment with anti-CTLA-4 therapy." (PMID 24883190, 2014). "The effects of antibody-mediated blockade of CD1d on DC number and phenotype, priming of anti-tumor T cells, and tumor response to treatment with local radiotherapy and anti-CTLA-4 antibody were evaluated." (PMID 25349699, 2014). "CTLA-4 (amplicon length: 920 base pairs (bp)) was strongly expressed in CT26 tumor tissues compared with normal colon tissues." (PMID 25365349, 2014). "First, CTLA-4 expression was examined in CT26 tumor tissues and cultured CT26 cells by reverse transcription polymerase chain reaction (RT-PCR) analysis." (PMID 25365349, 2014). "In conclusion, this study demonstrates that tumor-specific immune responses play an important role in the therapeutic efficacy of irradiation, which can be augmented by immune checkpoint (CTLA-4) inhibition." (PMID 24686897, 2014).
tumor (continued). "Together, the results indicate that 64Cu-DOTA-anti-CTLA-4 mAb would be useful for the evaluation of CTLA-4 expression in tumor." (PMID 25365349, 2014). "To improve anti-tumor effects of therapeutic vaccine, we fused cytotoxic T-lymphocyte antigen 4 (CTLA-4) with HPV16 E7 and E6 as a fusion therapeutic DNA vaccine (pCTLA4-E7E6)." (PMID 25265018, 2014). "Taken together with our results, these findings indicate that irradiation-induced anti-tumor immunity can be augmented by CTLA-4 blockade and that the resulting enhanced immunity acts both locally and systemically." (PMID 24686897, 2014). "GITR is similar to programmed cell death-1 (PD-1) and cytotoxic T-lymphocyte antigen 4 (CTLA-4), both of which have been applied clinically as immune modifiers in tumor therapy." (PMID 25105508, 2014). "This increase in anti-tumor activity by CTLA-4 blockade is due to a combination of direct activation of effector T cell function and concomitant inhibition of regulatory T cell (Treg) activity." (PMID 24686897, 2014). "First pre-clinical studies of the combination of these antibodies to achieve blockade of both CTLA-4 and PD-1 showed increased tumor infiltration by CD4+ and CD8+ T-cells, enhanced IFNγ and TNFα production, and reduced amounts of Tregs." (PMID 24822170, 2014). "T-cell co-receptor cytotoxic T-cell antigen-4 (CTLA-4) is a critical inhibitory regulator of T-cell immunity and antibody blockade of the co-receptor has been shown to be effective in tumor immunotherapy." (PMID 25538704, 2014). "Ex-vivo biodistribution analysis also revealed that 64Cu-DOTA-anti-CTLA-4 mAb showed significant accumulation in the CT26 tumor compared to 64Cu-DOTA-Control IgG." (PMID 25365349, 2014). "Our results demonstrated that 64Cu-DOTA-anti-CTLA-4 mAb visualized CTLA-4 expression in CT26 tumor in a noninvasive manner." (PMID 25365349, 2014). "Inhibition of CTLA-4 and PD-1 binding to their ligands enhances T-cell activation and proliferation, leading to tumor infiltration by T-cells and tumor regression." (PMID 25331657, 2014). "Early work in the field led by Allison and colleagues showed that in preclinical models blockade of CTLA-4 induces an anti-tumor immune response." (PMID 24883190, 2014). "A second possibility is that the administration of anti-CTLA-4 results in a compensatory expansion of the Treg compartment and thus prevents generation of an effective anti-tumor response when GVAX vaccine is administered later." (PMID 23557194, 2013). "On that basis we proposed that anti-CTLA-4 antibody therapy in combination with the E6-RHDV-VLP-PADRE vaccination would enhance the anti-tumour response to HPV." (PMID 23799135, 2013). "FoxP3+TREG cells within tumor burden express elevated levels of multiple suppressive receptors such as PD-1, CTLA-4, TIM-3, LAG-3, and GITR." (PMID 23616948, 2013). "Eleven EOC patients, previously vaccinated with GM-CSF and irradiated autologous tumor cells, received anti-CTLA-4 ipilimumab (Yervoy®, Bristol-Myers-Squibb, BMS)." (PMID 23763830, 2013). "We also showed that CTLA-4 engagement with B7 ligands induces tumor cell death through apoptosis suggesting a functional role of CTLA-4 molecule also in tumor cells." (PMID 23634660, 2013). "CTLA-4 blockade enhances T cell activation and memory against a poorly immunogenic spontaneous murine tumor and generates antitumor T-cell responses in early stages of tumor growth." (PMID 24216992, 2013). "CTLA-4 polymorphisms are associated with various cancers, and CTLA-4 mRNA/protein increased expression is found in several tumor types." (PMID 23936819, 2013). "Based on these data, we concluded that the treatment regimen that produced optimal CD8 T cell anti-tumor activity was day 0 GVAX followed by twice per week anti-CTLA-4 mAb at the dose of 3 mg/kg." (PMID 23557194, 2013).
tumor (continued). "By binding to CTLA-4, ipilimumab interrupts the transmission of B7-CTLA-4-mediated inhibitory T cell signalling, resulting in unopposed activation of T cells and stimulation of anti-tumour immune responses." (PMID 24276125, 2013). "Our data show that GVAX + anti-CTLA-4 combination therapy mitigates peripheral tolerance and promotes the activation and proliferation of tumor antigen-specific CD8 T cells." (PMID 23557194, 2013). "Although a previous animal study did find enhanced anti-tumor efficacy when anti-CTLA4 was added to melphalan chemotherapy, this experiment used a subtherapeutic dose of melphalan, intended to skew T cell responses towards a Th1 phenotype." (PMID 23626745, 2013). "We also found the median tumour survival was increased by around 50 % with the inclusion of CTLA-4 treatment." (PMID 23799135, 2013). "In mice, fractionated RT to a tumor on one flank with concurrent administration of anti-CTLA-4 antibody induced activated tumor-specific T cells and inhibited growth of tumors on the contralateral flank, located outside of the radiation field." (PMID 24403263, 2013). "We found that the tumour area was reduced by around a third at day 44 in the E6-RHDV-VLP-PADRE vaccinated mice treated with anti-CTLA-4, compared with E6-RHDV-VLP-PADRE vaccinated mice treated with an isotype control antibody (M-W U test; P<0.005)." (PMID 23799135, 2013). "Even in patients with tumours showing cPRs, the % of CTLA-4+ Tregs were 3 fold elevated, compared with HFDs (p = 0.015)." (PMID 23320561, 2013). "Since agonistic anti-4-1BB antibodies appear to both improve anti-tumor responses and, in some cases, reduce autoimmunity, it has been suggested to combine this treatment with antibodies blocking CTLA-4." (PMID 23785471, 2013). "Treatment with anti-CTLA-4 alone reduced the rate of tumor growth but was less effective than gemcitabine as a monotherapy." (PMID 23626745, 2013). "Further, combination of a 4-1BBL-expressing tumor cell vaccine with antibody-mediated blockade of CTLA-4 proved superior to tumor cell vaccine alone." (PMID 23840967, 2013). "In these tumor studies, blocking CTLA4 enhanced CTL-mediated death of tumor cells, a reason for the development of anti-CTLA4 treatment in the clinic." (PMID 24314019, 2013). "These pathways as well as innate and adaptive immune responses demonstrated by T-cell activation have become an area of active research, with antibodies against CTLA-4 and PD-1 showing clinical efficacy and anti-tumour activity." (PMID 23526956, 2013). "We also focused on the associations between CTLA-4 expression and gene polymorphic variants and NSCLC patients characteristics, as well as tumor clinical staging." (PMID 23936819, 2013). "In contrast to CTLA-4, PD-1 signaling occurs in the tumor, where PD-L1-expressing tumor cells can signal through PD-1 on TIL to turn-down the antitumor T-cell response." (PMID 23763830, 2013). "NAC (ACT, ACTCap) significantly reduced Tregs (% FOXP3+, AbN CTLA-4+), but only after 8 cycles and following a complete or substantial reduction in tumour mass." (PMID 23320561, 2013). "Nevertheless, CTLA-4 blockade efficacy in tumor therapy was correlated with the stage and immunogenicity of the tumor." (PMID 23450201, 2013). "In our study we showed allelic and genotypic distribution of +49 and −318 CTLA-4 SNPs in a group of NSCLC patients of Caucasian origin and revealed CTLA-4 genotype distribution shift from one genotype in the blood to another genotype in the tumor." (PMID 23936819, 2013). "The systemic administration of anti-CTLA-4 antibody therefore enhanced the therapeutic anti-tumour effect afforded by E6-RHDV-VLP-PADRE." (PMID 23799135, 2013). "Although previous preclinical studies have demonstrated that CTLA-4 blockade augments the anti-tumor effects of GVAX, to our knowledge this is the first study to report extensively on the importance of timing and dosage in this treatment regimen." (PMID 23557194, 2013).
tumor (continued). "Treatment with anti-Tim-3 Ab alone or in combination with anti-CTLA-4 and/or PD-1 Abs significantly suppressed tumor growth in mice." (PMID 23526963, 2013). "Targeting the CTLA-4 signaling pathway has, in other studies, yielded promising results in overcoming suppressive immunological responses against tumours." (PMID 23799135, 2013). "TIM-3 blocking antibodies result in enhanced anti-tumor T cell responses and control of tumor growth in murine solid cancer models, especially when combined with PD-1 and CTLA-4-blocking antibodies." (PMID 24353898, 2013). "In this study we show for the first time that CTLA-4 blockade and immunopotentiating chemotherapy in a therapeutic dose have a synergistic effect, resulting in the induction of a potent anti-tumor immune response and long-term protective immunity." (PMID 23626745, 2013). "At early stages small tumors were sensitive to the effects of CTLA-4 blockade, whereas advanced tumors were resistant due to the strongly tumor-induced T cell tolerance." (PMID 23450201, 2013). "Given the multitude of suppressive mechanisms, it is remarkable that a relatively high proportion of patients can achieve objective tumor responses by blockade of a single pathway, such as PD-1/PD-L1 or CTLA-4." (PMID 24194739, 2013). "Taken together, these data demonstrate that anti-CTLA-4 and chemotherapy synergize in the induction of a potent anti-tumor immune response, with an important role for both CD4+ and CD8+ T cells for optimal therapeutic effect." (PMID 23626745, 2013). "Combined anti-CTLA-4 application and Treg depletion resulted in maximal tumor rejection, which was dependent on the expansion of tumor-specific CD8+ T cells." (PMID 23450201, 2013). "It has been shown that tumor ablation in combination with anti-CTLA-4 antibody leads to enhanced anti-tumor immunity in the B16 model." (PMID 23874673, 2013). "Human trials that used a blocking anti-CTLA-4 mAb demonstrated a reduction in tumor mass and clinical benefit in a substantial minority of treated subjects." (PMID 23289632, 2013). "Blockade of CTLA-4 enhances tumor immunity in animal models of cancer, which is thought to rely on the enhancement of effector T cell activity, and the inhibition or deletion of regulatory T cells." (PMID 24353898, 2013). "In essence, CTLA4 and PD-1 represent two examples of successful targeting of molecules expressed in the TM in order to inhibit tumor growth." (PMID 23805414, 2013). "Surprisingly, when only the first dose of gemcitabine was omitted (as in the ‘anti-CTLA-4 first’ arm versus the concomitant arm), the anti-tumor effect decreased dramatically." (PMID 23626745, 2013). "Pre-clinical studies have demonstrated that CTLA4 blockade in vivo is followed by significantly increased anti-tumor immune response when the tumor is highly immunogenic." (PMID 23805414, 2013). "We found here that combination therapy of gemcitabine and anti-CTLA-4 exerted a far greater anti-tumor effect than either of the agents alone, thus acting in a synergistic manner." (PMID 23626745, 2013). "Early clinical trials in metastatic melanoma and ovarian carcinoma patients demonstrated that blocking CTLA-4 resulted in extensive tumor necrosis with lymphocyte and granulocyte infiltrates in a large number of patients." (PMID 23450201, 2013). "Alternatively, antibodies that block inhibitory T cell receptors, like CTLA-4, and strategies that eliminate suppressive cell types within the tumor microenvironment, like Tregs, improve T cell effector functions." (PMID 23935927, 2013). "Further, there have been significant advances in cancer immunotherapyusing antibodies to block CTLA4 or PD-1 co-inhibitory function, thereby augmentinganti-tumor immunity." (PMID 24004819, 2013). "The highest level of post-NAC circulating CTLA-4+ Tregs (1.69 ± 0.25%) was seen in patients whose tumours had a poor pathological response." (PMID 23320561, 2013).
tumor (continued). "The data herein support the validity of combining chemotherapy with CTLA-4 blockade to mediate tumor regression and suggest further clinical study of these regimens for the treatment of cancer is warranted." (PMID 23873089, 2013). "Despite its apparent role in attenuating T cell activation, CTLA-4 seems to be required for effective anti-tumor immunity, as this molecule also affects T cell polarization." (PMID 24348481, 2013). "Combinatorial blockade with anti-CTLA-4 and anti-PD-1 monoclonal antibodies can be potently synergistic in some tumor models." (PMID 24829752, 2013). "The heterogeneity of CTLA-4 expression can be considered as an intrinsic biological characteristic of the tumor." (PMID 23634660, 2013). "Activated tumor-infiltrating Tregs were found to express higher levels of CTLA-4, GITR and PD-1, which were observed in the Tim-3+Foxp3+ CD4 T cells." (PMID 23526963, 2013). "The results reported here demonstrate synergy between specific chemotherapeutic agents and CTLA-4 blockade in tumor regression." (PMID 23873089, 2013). "Preliminary data from our laboratory have indicated that IDO inhibition combined with either anti-CTLA-4 or anti-PD-L1 monoclonal antibodies can also result in potent immune-mediated tumor control in vivo [authors’ unpublished observations]." (PMID 24829752, 2013). "Anti-CTLA-4 antagonist mAb (ipilimumab), though proven to be effective in reducing the presence of Tregs within tumor, actually expands the overall number of Treg cells." (PMID 22778760, 2012). "Stimulation of tumor-expressed CTLA-4 with soluble ligands or agonistic mAb leads to induction of apoptosis as well as inhibition of proliferation and secretion of angiogenic cytokines." (PMID 22778766, 2012). "We found that 4-1BBL-expressing tumor vaccine in combination with CTLA-4 blockade was effective in reducing tumor incidence and increasing in survival of the tumour cell recipients." (PMID 22312406, 2012). "Patients with metastatic melanoma showed improved antitumor immunity and tumor regression by blockade of CTLA-4 together with peptide vaccination." (PMID 22481922, 2012). "In vivo administration of anti-CTLA4 antibody resulted in tumor rejection including preestablished tumors." (PMID 22481922, 2012). "Two monoclonal antibodies against human CTLA-4, ipilimumab and tremelimumab, have been reported to elicit objective and durable responses against tumor cells in clinical trials." (PMID 22489248, 2012). "Initial human clinical trials assessing the effects of a blocking anti-CTLA-4 antibody demonstrated not only a reduction in tumor mass and clinical benefit in a minority of treated subjects but also an increase in systemic inflammation." (PMID 22548114, 2012). "CTLA-4 blockade causes a dynamic shift in the ratio between Tregs and CD8+ TCLs culminating in effective immune recognition of neoplasms." (PMID 22046181, 2012). "Aptamer inhibition of cytotoxic T-cell antigen 4 (CTLA-4) is one approach to prevent immune system inactivation and promote tumor elimination." (PMID 23130020, 2012). "Combinations of RT with antibodies blocking inhibitory negative regulatory molecules on T cells, such as the monoclonal antibody ipilimumab against CTLA-4, are promising to induce systemic anti-tumor immune responses." (PMID 22848871, 2012). "Since it is likely that many of those total CD8 T-cells from TILN are tumor specific, our data suggest that they frequently express inhibitory receptors such as CTLA-4, LAG-3, PD-1, TIM-3, BTLA and 2B4." (PMID 22347406, 2012). "Blocking CTLA-4 is thought to shift the balance of the immune response, enhancing both the recognition of tumour antigens and the neoplastic regression." (PMID 22046181, 2012). "This event was documented in posttreatment biopsies of neoplasms treated with CTLA-4 blockade and correlated with therapy-mediated tumoral necrosis." (PMID 22046181, 2012).